UTP3 (UTP3 small subunit processome component)
Description:
Essential for gene silencing: has a role in the structure of silenced chromatin. Plays a role in the developing brain (By similarity). Part of the small subunit (SSU) processome, first precursor of the small eukaryotic ribosomal subunit. During the assembly of the SSU processome in the nucleolus, many ribosome biogenesis factors, an RNA chaperone and ribosomal proteins associate with the nascent pre-rRNA and work in concert to generate RNA folding, modifications, rearrangements and cleavage as well as targeted degradation of pre-ribosomal RNA by the RNA exosome.
Synonyms: CRL1; CRLZ1; SAS10; FLJ23256; DKFZp761F222
Tractability: Small molecule: a structure with a bound ligand is known. PROTAC: UniProt records ubiquitination sites on it; ubiquitination databases record sites on it; its protein half-life has been measured.
Gene: Protein-coding gene on chromosome 4 (70,688,532 to 70,690,551, forward strand). Ensembl gene ENSG00000132467.
Subcellular location: Nucleus, nucleolus
Subcellular location (Human Protein Atlas): Nucleoli; Vesicles
Pathways (Reactome):
Metabolism of RNA: Major pathway of rRNA processing in the nucleolus and cytosol; rRNA modification in the nucleus and cytosol
Gene Ontology:
Molecular function: protein binding; RNA binding
Biological process: ribosomal small subunit biogenesis; brain development; maturation of SSU-rRNA; maturation of SSU-rRNA from tricistronic rRNA transcript (SSU-rRNA, 5.8S rRNA, LSU-rRNA)
Cellular component: nucleolus; small-subunit processome; nucleoplasm; nucleus
Genetic constraint (gnomAD): Loss-of-function variants: 19 observed, 40.16 expected, observed/expected ratio (o/e) 0.47, 90% interval 0.33 to 0.69. The upper end of that interval is the gene's LOEUF score, 0.69, which puts it in group 2 of 6, group 1 being the genes least tolerant of losing a copy. Missense variants: 504 observed, 605.4 expected, observed/expected ratio (o/e) 0.83, 90% interval 0.77 to 0.9. Synonymous variants: 242 observed, 232.69 expected, observed/expected ratio (o/e) 1.04, 90% interval 0.94 to 1.16.
Homologues: Orthologues: dog UTP3 (89% identical), pig UTP3 (88% identical), mouse Utp3 (86% identical), rat Utp3 (85% identical), guinea pig UTP3 (84% identical), rabbit UTP3 (83% identical), tropical clawed frog utp3 (50% identical), zebrafish utp3 (48% identical), Drosophila melanogaster Sas10 (32% identical). Paralogues in human: NGDN (14% identical).
Diseases named in the same sentence as UTP3 in open-access papers:
UTP3 is named in the same sentence as 13 diseases in open-access papers, as found by Europe PMC text mining. Sharing a sentence is not in itself a finding about the gene and the disease. The quoted sentences say what the papers report.
esophageal squamous cell carcinoma (2 papers, 2024 to 2025). Esophageal squamous cell carcinoma (ESCC) is a type of esophageal carcinoma (EC) that can affect any part of the esophagus, but is usually located in the upper or middle third. "In a study on drug resistance factors of esophageal squamous cell carcinoma, it was found that the expression of UTP3 in drug-resistant cancer cells was significantly higher than that in drug-sensitive cells." (PMID 39852139, 2025).
colorectal cancer (1 paper, 2021). A primary or metastatic malignant neoplasm that affects the colon or rectum. "UTP3 was proved to be involved in the pathogenesis of colorectal cancer and ADAMDEC1 was a positive regulator of epithelial defense against cancer and plays an active role in inhibiting glioblastoma development." (PMID 33592580, 2021).
osteosarcoma (1 paper, 2021). A usually aggressive malignant bone-forming mesenchymal neoplasm, predominantly affecting adolescents and young adults. "Utp3 is involved in the development of the osteosarcoma through regulating the ribosome biogenesis." (PMID 34707778, 2021).
UTP3 also shares sentences with these, for which no sentence is quoted: cancer (3 papers); anemia (1); B cell lymphoma (1); Burkitt lymphoma (1); fungal infection (1); glioblastoma (1); lymphoma (1); migraine (1); retinal degeneration (1); tumor (1).